SEMA6B (semaphorin 6B)
Diseases named in the same sentence as SEMA6B in open-access papers (continued):
Sharing a sentence is not in itself a finding about the gene and the disease.
tumor (17 papers, 2021 to 2025). "Experiment results indicated that SEMA6B high expression was significantly associated with pDC, NK cells eosinophils infiltration signature in the tumor microenvironment." (PMID 37155149, 2023). "In this context, high SEMA6B expression may reflect an aggressive tumor phenotype associated with stromal remodeling and immune evasion." (PMID 40564066, 2025). "Functional enrichment analysis and the Estimation of STromal and Immune cells in MAlignant Tumor tissues using Expression data (ESTIMATE) algorithm revealed that the gene cluster associated with the high SEMA6B group were prominently involved in immune responses and inflammatory activities." (PMID 34938771, 2021). "Moreover, we explored the underlying biological functions and relevant pathways of SEMA6B and investigated correlations of SEMA6B with a variety of tumor-infiltrating immune cells (TIICS) as well as tumor-immunity status via comprehensive bioinformatic analyses." (PMID 34938771, 2021). "Among them, SEMA6B was significantly downregulated in tumor tissues compared to normal samples (p < 0.01)." (PMID 40564066, 2025). "One plausible explanation is that SEMA6B is downregulated during early tumor development but re-expressed in later stages under immune-selective pressure, contributing to immune escape and tumor dissemination." (PMID 40564066, 2025). "In this study, we compared the expression of SEMA6B in paired adjacent normal tissue and tumor samples from THCA patients." (PMID 37155149, 2023). "The validation part demonstrated that ADAMTSL4, DOCK6, FAM111B, and SEMA6B were expressed at higher levels in the tumor tissue, whereas lower expression of MRPS10 and PSMB7 was observed." (PMID 36761753, 2023). "It was reported that sema6B-plexinA4 signal promoted tumor angiogenesis by regulating VEGF-induced VEGFR-2 phosphorylation in endothelial cells." (PMID 35350431, 2022). "In the present study, we revealed that high SEMA6B expression was positively associated with higher stromal scores, immune scores, and ESTIMATE scores but was negatively association with tumor purity." (PMID 34938771, 2021). "In particular, SEMA6B may facilitate tumor progression by modulating semaphorin–plexin signaling, which is known to influence immune suppression, angiogenesis, and cell motility." (PMID 40564066, 2025). "SEMA6B was significantly downregulated in the tumour group but may be reactivated during metastasis." (PMID 40564066, 2025). "Upregulation of SEMA6B in cancer may promote tumor growth and metastasis by increasing cell migration and invasion." (PMID 37240140, 2023). "Semaphorin 6b (SEMA6B) is a member of the semaphoring axon-guidance family and was initially characterized as an axon guidance factor with axon navigation functions but has also been demonstrated to induce or inhibit tumor progression." (PMID 37760246, 2023). "In addition, comparison of enrichment scores also provided consistent results that SEMA6B high-expression tumor samples exhibited significantly higher enrichment scores involving pDC\NK cells\eosinophils infiltrations." (PMID 37155149, 2023). "Human Sema6B is highly expressed in human brain and regulates tumor growth." (PMID 35350431, 2022). "Both sets of results suggested that elevated miR-30b/-30d enhanced the protein expression of E-cadherin, while reducing that of SEMA6B, N-cadherin, and vimentin in subcutaneous xenotransplanted tumor tissues, which was abrogated by the overexpression of SEMA6B." (PMID 33738326, 2021). "Likewise, the relationships between gene markers of different immune cells and SEMA6B expression are suggestive of a pivotal role of SEMA6B in regulating the tumor immune microenvironment." (PMID 34938771, 2021). "Overexpression of SEMA6B in BHK-21 cells could promote cell proliferation, and the inhibition of SEMA6B signaling suppresses tumor formation for the sake of abrogation of bFGF and VEGF signaling." (PMID 34938771, 2021).
tumor (continued). "To further determine the influence of SEMA6B on the tumor microenvironment, we investigated correlations between SEMA6B and expression of genes negatively regulating the cancer-immunity cycle, which consists of a cycle of processes involving eradication of cancer by the immune system." (PMID 34938771, 2021). "In addition, the tumor cell apoptosis was promoted by knocking down SEMA6B." (PMID 37155149, 2023). "Hence, accumulating evidence suggests that SEMA6B may contribute to tumor development by both attenuation of tumor-specific cytotoxic T-cell responses and induction of an immunosuppressive state." (PMID 34938771, 2021). "We have also previously found that silencing the expression of the plexin-A2/plexin-A4 ligand sema6B in U87MG cells results in the inhibition of proliferation and tumor formation." (PMID 36658114, 2023). "SEMA6B expression was positively correlated with stromal scores, immune scores, and ESTIMATE scores, while SEMA6B expression was negatively correlated with tumor purities." (PMID 34938771, 2021). "This may partially explain why knocking out SEMA6B, MT1E, S100A4, or ASAH2 may significantly promote tumor colony growth." (PMID 39605490, 2024). "Semaphorin 6b (SEMA6B) promotes and suppresses tumor progression." (PMID 36761753, 2023). "Finally, we established subcutaneous xenotransplanted tumor models of untreated GBC-SD cells, miR-30b/-30d mimic-treated GBC-SD cells, and GBC-SD cells treated with miR-30b/-30d mimic in addition to an expression vector containing the SEMA6B gene." (PMID 33738326, 2021). "Correlations between SEMA6B expression and components of the tumor immune microenvironment were analyzed by packages implemented in R, Tumor Immune Estimation Resource (TIMER), Gene Expression Profiling Interactive Analysis (GEPIA), and Tumor-Immune System Interactions database (TISIDB)." (PMID 34938771, 2021). "They investigated the expression in the TME of 3 Plexin-A4 ligands, namely Sema3A, Sema6A, and Sema6B, and found that none of them modulated CD8+ T cell infiltration into the tumor bed." (PMID 38329122, 2024). "However, SEMA6B expression in CRC was not significantly correlated with other clinicopathological characteristics, including age, gender, tumor site, lymphatic invasion, M stage, N stage, pathological stage, and patient status." (PMID 34938771, 2021).
cancer (7 papers, 2016 to 2024). A tumor composed of atypical neoplastic, often pleomorphic cells that invade other tissues. "Upregulation of SEMA6B was frequently associated with increased invasiveness, metastasis, and migration of cancer cells and worse overall prognosis." (PMID 38067240, 2023). "The correlation heatmap showed that PDE2A was positively associated with SEMA6B, RUNDC3B, MICU3, and KCNK3 genes in the majority of cancers." (PMID 39699377, 2024). "In other words, due to reciprocal plexin-A4 coreceptor activity, SEMA6B plays a substantial role in cancer vascularization and responsiveness to environmental stimuli." (PMID 38067240, 2023). "SEMA6B, a member of the semaphorin axon-guidance family, has recently been investigated in terms of human SEMA6B gene expression and its roles in cancer." (PMID 34938771, 2021). "Unsupervised hierarchical clustering analyses revealed that genes involved in the negative regulation of the cancer-immunity cycle were mostly upregulated in the high SEMA6B expression group." (PMID 34938771, 2021). "Given that our knowledge of the role of SEMA6B in cancers is limited, in the present study, we aimed at investigating its prognostic value in CRC and revealed its associated biological functions by performing a comprehensive analysis of population databases." (PMID 34938771, 2021). "Subsequently, the Kaplan-Meier plotter database was used to analyze the prognostic potential of SEMA6B in different cancers." (PMID 34938771, 2021). "Our data revealed that high SEMA6B expression was significantly correlated with cancer progression, poor survival, and immune infiltration in patients with CRC." (PMID 34938771, 2021). "Biological pathway analysis and functional enrichment analysis in our present study illustrated that immune-related processes, inflammatory activities, and cancer signaling pathways were significantly enriched in the high SEMA6B expression group." (PMID 34938771, 2021). "The identification of SEMA6B, RUNDC3B, MICU3, and KCNK3 as top PDE2A-correlated genes provided novel targets for functional validation studies aimed at elucidating the molecular mechanisms underlying PDE2A's role in cancer." (PMID 39699377, 2024). "Among the members of the SEMA6 family, SEMA6B and SEMA6D have been implicated in cancer formation." (PMID 35269749, 2022). "While enhanced SEMA6B improved cancer cell viability and invasiveness through the modulation of the NOTCH pathway, silencing of SEMA6B made cancer cells less viable and invasive." (PMID 38067240, 2023).
infection (3 papers, 2021 to 2024). The state of being infected such as from the introduction of a foreign agent such as serum, vaccine, antigenic substance or organism. "The function of Sema6b in infection is poorly studied, and the available data only focuses on the relevance of this receptor in sensitivity to the Paeniclostridium (Clostridium) sordelii pathogen." (PMID 39768135, 2024).
SEMA6B also shares sentences with these, for which no sentence is quoted: gastric tumor (2 papers); acute-on-chronic liver failure (1); breast adenocarcinoma (1); cardiovascular disease (1); colorectal (1); early-onset epilepsy (1); liver cirrhosis (1); lung squamous cell carcinoma (1); lymph node metastasis (1); microcephaly (1); neuroblastoma (1); thyroid tumor (1).